IL6 (interleukin 6)
Diseases named in the same sentence as IL6 in open-access papers (continued):
Sharing a sentence is not in itself a finding about the gene and the disease.
tumor (continued). "Our study showed that PCT and IL-6 may serve as indicators of neoplastic disease, but their role as prognostic biomarkers needs to be further explored." (PMID 26148092, 2015). "Within the tumor microenvironment, the immunosuppressive milieu is further enhanced by the production of interleukin 10 (IL-10), which together with IL-4, IL-6, and IL-13 cytokines induces monocyte differentiation toward a mature M2-polarized phenotype that is characteristic of TAMs." (PMID 28536400, 2015). "In the phase 2/3 study IL-6 was shown to be both prognostic as well as predictive for Nap activity since the subgroup and a trend analysis clearly supported that low baseline anti-SEA/E-120 and IL-6 plasma levels independently predict anti-tumour efficacy after Nap+IFN-α treatment." (PMID 25669986, 2015). "In fact, stimulation of HPFs with the medium of castration-resistant PCa cells was sufficient to increase α-SMA and FAP expression and to promote the acquisition of tumor-promoting properties, a phenotype abrogated by the administration of an anti-IL6 antibody." (PMID 26375444, 2015). "Taken together, the results have demonstrated that EAT growth is modulated by PGE2 and the inhibition of the tumor growth could be partly related to suppression of IL-6 and induction of IL-13." (PMID 26347589, 2015). "Although the relationship between IL-6 and cancer has been extensively studied, the role of the production of this interleukin in the microenvironment of the tumor which progresses via malignant cells and tumoral infiltrated lymphocytes and macrophages is still controversial." (PMID 26082901, 2015). "We have previously shown that monocytes are stimulated to secrete IL-6 upon HNSCC tumor co-culture." (PMID 26079381, 2015). "The peritumoral expression of IL-6 gradually increased during tumor growth." (PMID 26525581, 2015). "IL-6 is one of the best-characterized pro-inflammatory cytokines and our results strongly suggest that after high dose of radiation stromal cells are able to modify the milieu and induce tumor cells to secrete factors able to alter immune infiltrate." (PMID 25635683, 2015). "However, when immunized in aged IL-6−/− mice, their efficacy was significantly improved, suggesting that increased IL-6 levels in aged hosts dampened the function of tumour-specific CD4+ T cells." (PMID 25850032, 2015). "Previous studies have showed that EP2 could promote cell growth and invasion through upregulation of the tumor-promoting inflammatory cytokines, such as IL-1β and IL-6." (PMID 25781635, 2015). "For example, among cytokines, which are major immune players, IL6 and IL10 are known to cause immune suppression or tolerance, leading to tumor progression, whereas IL2, IL12, IL23, interferon (INF)-alpha and INF-gamma are crucial in immune activation, leading to tumor suppression." (PMID 26674411, 2015). "IL-6 is a pleiotropic cytokine that modulates the phenotype of many cancer types by binding to IL-6 receptors and activating downstream pathways, thereby promoting tumor initiation, development, and metastasis." (PMID 26512918, 2015). "H&E staining of the tumor tissue in each group revealed that the tissue structure was orderly and tightly organized in the control and hucMSC groups, whereas it was obviously loose and messy in the IL-6-hUC-MSC group." (PMID 25483835, 2015). "Similarly, IL-6 induction by PDT was associated with cell death inhibition and enhanced tumor growth in human basal cell carcinoma (BCC-1/KMC) cells and mice bearing subdermal Co26 murine colon carcinomas or 4T1 mammary carcinomas." (PMID 26516076, 2015). "M2 macrophages promote tumor progression by enhancing angiogenesis and inhibiting an immune response against tumors, whereas M1 macrophages promote a proinflammatory microenvironment by releasing IL-1β, IL-6, IL-12, and tumor necrosis factor alpha (TNF-α)." (PMID 26131447, 2015). "This impact on IL-6 level further changed the Th17 cell proportion in tumor microenvironment." (PMID 25826372, 2015).
tumor (continued). "Similarly, Interleukin 6 (IL-6) and Interleukin 8 (IL-8) expression transiently increased, peaked around day 8, and decreased upon tumor regrowth, however, remained above pre-treatment levels." (PMID 28203638, 2015). "Likewise, renal RFA-induced increases in serum IL-6 levels and distant R3230 tumor growth was suppressed with anti-IL6 siRNA (p<0.01)." (PMID 26154425, 2015). "It is well-known that a controversy has been existed for a long time around the question of whether IL-6 and IL-17A are anti-tumor or tumor promoting factors." (PMID 25826372, 2015). "In addition and interestingly RhoB deficiency in the stroma enhanced tumor cell migration but simultaneously stimulated pro-inflammatory signals (IL-6) that would impact on immune recruitment and favor anti-tumor immune response." (PMID 25635683, 2015). "In addition to the stimulating effects of IL-6 and IGF-1, loss of function mutations of the tumour suppression gene PTEN in several MM cell lines, results in phosphorylation of the mTOR substrates." (PMID 26097872, 2015). "Importantly, when Th1 differentiation was restored by the blockade of IL-6 or subsequent IL-4/IL-21 activities, induction of tumour-specific aged CD8+ T cells was enhanced as well, implying minimum intrinsic functional defects in aged CD8+ T cells." (PMID 25850032, 2015). "Although IL-6 did not diminish or promote in vivo expansion of CD4+ T cells in response to vaccination, the age-associated increase in IL-6 dampened Th1 differentiation of CD4+ T cells and subsequent induction of tumour-specific CD8+ T cells, and thereby promoted cancer progression in aged mice." (PMID 25850032, 2015). "Moreover, OCT4B enhanced angiogenesis by the upregulation of CD34, VEGF, HIF-1α and IL-6, and promoted tumor cell mobility to the surrounding tissue by the upregulation of MMP2 and MMP9, and the induction of epithelial-mesenchymal transition (EMT)." (PMID 25816351, 2015). "A prevalent paradigm in tumor biology is that TECs may have a much higher proliferation rate when responding to pro-angiogenic factors, such as IL-6 or sIL-6R." (PMID 26525581, 2015). "IL-6 activates STAT3 constitutively both in tumor cells and immune cells." (PMID 25685909, 2015). "Serum IL-6 concentration might correlate with the stage of tumour proliferation in patients with HNSCC and can be useful in the detection of metastases." (PMID 25858079, 2015). "Secretion of miR-21 from tumor-cell-derived exosomes or up-regulation of miR-21 in TAMs by tumor-derived pro-inflammatory products such as IL-6 or TNF, may participate in TAM reprograming and thereby facilitate growth, intravasation, and spread of tumor cells." (PMID 25688245, 2015). "In summary, this study demonstrates that miR-22, as an endogenous microRNA of DCs, could suppress the translation of p38 mRNA and further down-regulate the expression of IL-6, which in turn interferes with Th17 cell development in tumor microenvironment." (PMID 25826372, 2015). "However, IL-6, IGF-1, and IL-21 are associated with tumor cell survival and resistance to apoptosis." (PMID 26649299, 2015). "We propose that at inflammatory sites which include atherosclerotic plaques or tumor growth sites, these lipids might exert anti-inflammatory effects such as inhibiting the release of the pro-inflammatory cytokine IL-6 by recruited monocytes." (PMID 25251539, 2014). "To determine the key factors for enhanced tumor growth in microenvironment, we performed comprehensive multiplex assays involving the co-culture supernatants and observed significant elevation of the levels of several cytokines, including interleukin-6 (IL6)." (PMID 24885802, 2014). "Finally, it has been shown that administration of IL-6 neutralizing antibodies or IL-6 inhibitors can reduce muscle wasting in tumor-bearing mice." (PMID 24967341, 2014).
tumor (continued). "Furthermore, IHC analysis revealed that increased densities of IL-6 and NF-κB positive cells were observed in both the transformed epithelium and the tumor stroma, which are consistent with the findings in similar CAC mouse models reported by other groups." (PMID 25093140, 2014). "Indeed, hematopoietic stem cells or progenitor cells require several growth factors, such as insulin, IL-3, IL-6, G-CSF and GM-CSF, but these are dispensable for the culture of tumor initiating cells." (PMID 24466252, 2014). "The results confirmed the IHC observations and demonstrated increased expression of NF-κB and IL-6 proteins in the tumor tissues that was started after induction for 14 weeks and became more significant in the experimental terminal (after induction for 22 weeks)." (PMID 25093140, 2014). "Nevertheless, the TP-overexpressing tumor cells exhibited enhanced expression of IL-1β and IL-6." (PMID 24819505, 2014). "Importantly, metformin inhibited tumor growth and distant metastases in tumor-bearing nude mice and reversed IL-6-induced EMT both in vitro and in vivo." (PMID 24789104, 2014). "Besides its importance during early tumor promotion, IL-6 can also accelerate tumor growth during late stages of CAC via a direct stimulation effect on proliferation and growth of tumor cells." (PMID 25093140, 2014). "IL-6 is known to affect tumor migration by binding to cell-surface IL-6R molecules." (PMID 24398980, 2014). "Interleukin-6 in turn was predictive of tumour T, N and M status only in ER+ patients." (PMID 25338520, 2014). "In addition, we found that ICAM-1 acts as a crucial transducer of cell signaling that regulates cell migration, whereas IL-6 acts as a critical mediator of metastasis activity of OSCC cells in the tumor microenvironment." (PMID 24398980, 2014). "The tumor suppressor property of miR-29b may be partially explained by its inhibition on IL6-JAK-STAT3 signaling via targeting DNMTs and subsequent demethylation and activation of SOCS1." (PMID 24991558, 2014). "Moreover, IL-6 promotes the conversion of more differentiated tumor cells into CSCs, inducing the epithelial-to-mesenchymal transition (EMT)." (PMID 25136593, 2014). "Our data demonstrated that elevated IL-6 levels were associated with tumor recurrences but not with stages of the disease." (PMID 25547486, 2014). "SOCS1 is one of the most frequently methylated genes (65%) in HCCs, and the deletion of SOCS1 in tumour cells might enhance IL-6-mediated cell proliferation." (PMID 24757565, 2014). "Furthermore, IL-6 inhibition in tumor-bearing mice resulted in decreased tumor regrowth following irradiation." (PMID 25268165, 2014). "This in turn leads to increased IL-6 and IL-8 production in the tumor microenvironment." (PMID 26932376, 2014). "Autocrine secretion of IL-6 by tumor cells or the associated infiltrated cells, not only promotes tumor growth and invasion but also facilitates chemoresistance." (PMID 24782986, 2014). "However, IL-17A was significantly increased in draining lymph nodes of the irradiated group, compared to IL-6 and its expression exhibited a correlation with enhanced tumor growth." (PMID 25181290, 2014). "Increased serum levels of IL-6 has been correlated with increased levels of NF-κβ, which may represent a mechanism for tumour resistance to chemotherapy and radiotherapy." (PMID 25305747, 2014). "In particular, increased adipose tissue creates an oxidative environment that can upregulate the expression of various pro-inflammatory cytokines including TNF-α and IL-6, and this is critically associated with CRC development because these cytokines stimulate tumor growth and progression." (PMID 25515685, 2014). "Hence, the aim of this study was to investigate the impact of the IL6 SNPs rs1800797, rs1800796, rs1800795, rs2069849 and IL6 diplotypes based on these SNPs in relation to tumour ER-status on early events and treatment response." (PMID 25305747, 2014).
tumor (continued). "Furthermore, embelin, a derivative from Embelia ribes, is known to inhibit XIAP (X-linked inhibitor of apoptosis protein) and is able to impair tumor proliferation by interfering in IL-6/STAT3 signaling." (PMID 24901008, 2014). "LPA signaling may also exert its role in ovarian cancers indirectly through regulating telomerase, involved in tumor progress, IL-6 and IL-8 involved in tumor angiogenesis, or COX-2, correlated with possibility of metastasis." (PMID 24744506, 2014). "Furthermore, anti-IL-6 antibodies partially abrogated senescent MSC-CM-induced enhancement of tumor cell proliferation, migration and STAT-3 phosphorylation." (PMID 25419563, 2014). "Upregulation of IL-1β and IL-6 could potentially serve as autocrine positive feedback loop for TP in cancer cells and drive paracrine induction of the enzyme in tumor microenvironment." (PMID 24819505, 2014). "IL-6 is suggested to provide prognostic value based on its role as a tumor cell growth factor." (PMID 24683359, 2014). "IL-6 in turn affects tumor cells, stimulating their growth and resistance to chemotherapy." (PMID 25147739, 2014). "Tumor-related humoral factors, such as granulocyte colony-stimulating factor, interleukin-1, and interleukin-6, may play a role in stimulating megakaryocyte growth and platelet production." (PMID 24520974, 2014). "These include cytokines, chemokines and interleukins including interleukin 6 (IL-6), transforming growth factor-β (TGF-β), tumor necrosis factor-α (TNF-α), and interferon-γ (INF-γ), all of which are associated with chronic inflammation and tumor progression." (PMID 24523696, 2014). "Due to being one of the most ubiquitously deregulated cytokines in cancer, IL-6 is shown to modulate growth and differentiation in several malignant tumor cells and its overexpression with its receptors (IL-6R and sIL-6R) has been found in a wide range of cancers." (PMID 24670367, 2014). "Notably, tumors vascularized with IL-6-silenced endothelial cells showed lower intratumoral microvessel density, lower tumor cell proliferation, and slower growth than tumors vascularized with control endothelial cells." (PMID 24533454, 2014). "IL6 is reported as an autocrine growth or survival factor in several tumor types." (PMID 25093008, 2014). "In addition, these endothelial cells were co-transplanted with tumor cells into immunodefficient mice to determine the impact of endothelial cell-derived IL-6 on tumor growth and angiogenesis." (PMID 24533454, 2014). "Indeed, despite the fact that endothelial cells secrete many cytokines and growth factors, silencing of IL-6 with shRNA (or use of a netutralizing antibody) completely abrogated induced phosphorylation of STAT3 in tumor cells." (PMID 24533454, 2014). "Furthermore, MDSC expansion and MDSC-mediated liver injury further increased with growing tumor burden and was associated with different cytokines including GM-CSF, VEGF, interleukin-6, CCL2 and KC, depending on the tumor model used." (PMID 25401795, 2014). "IL-6 is believed to have a pro-tumor effect as well as an inflammatory effect." (PMID 25181290, 2014). "Secreted Hsp90 from PCa cell lines rapidly activates STAT3 in prostate fibroblast cell lines, leading to the activation of the pro-inflammatory NF-κβ pathway and secretion of inflammatory mediators known to augment PCa tumor survival and proliferation, such as IL-6 and IL-8." (PMID 24722453, 2014). "In the present studies focal irradiation of the tumor reduced the Th2 (IL-4 and IL-5) responses through B cells and inflammation (IL-6, IL-17, GM-CSF, IL-1α), which was accentuated by 2-DG besides removing the systemic immunosuppression through depletion of Tregs." (PMID 25248151, 2014). "The tumor aggressiveness noted in IL-6 positive OSCC may be in part via the overexpression of DNMT3b." (PMID 24625449, 2014).
tumor (continued). "Conversely, in the HER2-negative cohort, which is different from the HER2-positive arm for the biology of the tumor, the NC treatment, and also for the immune profile at diagnosis, we observed changes in IL-1α, IL-1β, IL-2, IL-6, and GM-CSF levels already at week 12 of ED treatment." (PMID 25512030, 2014). "We next set out to assess whether pre-irradiation of tumor beds can influence IL-6 levels in tumor-draining lymph nodes, as the lymph nodes, among lymphoid tissues, show the greatest involvement in mediating inflammatory responses." (PMID 25181290, 2014). "IL-6 is regarded as an important tumor-promoting factor in various types of human cancer." (PMID 25202430, 2014). "Finally, inhibition of IL-6 production in SKOV-3 cells reduced the ability of the tumor cells to suppress mixed leukocyte reactions." (PMID 24657910, 2014). "Chen and colleagues reported that some anti-inflammatory phytochemicals like EGCG appear to modulate the tumor microenvironment by repressing NF-kappaB (NF-κB, a proinflammatory transcription factor), and inhibiting pro-inflammatory cytokines like IL-6 and TNF-α in epithelial ovarian cancer." (PMID 25175005, 2014). "Conditioned medium from primary human dermal microvascular endothelial cells (HDMEC) stably transduced with silencing RNA for IL-6 (or controls) was used to evaluate the role of endothelial-derived IL-6 on the activation of key signaling pathways in tumor cells." (PMID 24533454, 2014). "In addition to its role in inflammatory disease, IL-6 signaling is also a key component of tumor cell proliferation." (PMID 24415766, 2014). "In tumor-bearing state, G-CSF/IL-6 could induce the protumor potential of neutrophils in bone marrow." (PMID 25587026, 2014). "To explore whether the function of neutrophils could be remodeled, we recruited neutrophils to the non-inflammatory and inflammatory peritoneal cavity of naive mice, tumor-bearing mice and the mice with in vivo expression of G-CSF and IL-6 (pG/pI6-mice)." (PMID 25587026, 2014). "siRNA-ISG15 remarkably inhibited VEGF and IL-6 production within tumor tissues." (PMID 25238261, 2014). "However, when exposed to hypoxia, IL6 shaped more macrophages differentiation into M2-like cells and functioned in promoting tumor angiogenesis and metastasis." (PMID 25313135, 2014). "IL-6 can also regulate the immune microenvironment surrounding the tumor." (PMID 25322805, 2014). "Previous studies have found that metformin could inhibit the expression of pro-inflammatory mediators, such as IL-6 and IL-17, which play important roles in tumor development, by reducing activation of NF-κB." (PMID 24789104, 2014). "IL-6 is a multifunctional cytokine which plays an important role in a wide range of biologic activities in different types of cell including inflammatory cells and tumor cells." (PMID 25238263, 2014). "In cancer, other molecules that may influence tumor growth by regulating the IL-6/STAT3 signaling pathway have been reported." (PMID 24901008, 2014). "The effects of interleukin (IL)-6 on tumor growth are multifaceted." (PMID 25322805, 2014). "In other words, downregulation of IL-6 secreted by endothelial cells inhibits phosphorylation of STAT3 in tumor cells, which will then secrete less angiogenic factors (e.g. CXCL8) causing a decrease in tumor microvessel density and tumor growth." (PMID 24533454, 2014). "However, this enhancement of tumor growth by IL-6 transfection was partially reversed by metformin treatment, indicating an inhibitory effect of metformin on IL-6-induced tumor growth." (PMID 24789104, 2014). "For example, a combination of TNF-α, IL-6, and IL-17 may compromise antitumor immunity and, if in sufficient levels throughout the tumor bed, promote tumor progression." (PMID 24955376, 2014). "Because MSCs express IL-6 receptors, high IL-6 concentrations in tumor tissues could directly induce the accumulation of MSCs in these tissues." (PMID 24502410, 2014).